PTH (parathyroid hormone)
Diseases named in the same sentence as PTH in open-access papers (continued):
Sharing a sentence is not in itself a finding about the gene and the disease.
osteoporosis (continued). "Also, there is a relative dearth of published evidence to foster a more detailed examination of the role of PTH and ARHGEF15 mutation in the association between osteoporosis and dementia pathophysiology." (PMID 40700291, 2025). "Furthermore, our osteoporosis group exhibited lower MHCa, i-PTH level, and even weight of the adenoma than the non-osteoporosis group." (PMID 41156271, 2025). "Thus, the current study, and our on-going studies in the laboratory, where we are investigating the crosstalk between PTH and Gi signaling pathways, will open new avenues for therapeutic targets in treating osteoporosis." (PMID 40668360, 2025). "The PTH BstBI AA genotype was also linked to significantly lower BMD in osteoporotic women compared to GA and GG genotypes (p = 0.01), making it a potential genetic marker for osteoporosis susceptibility." (PMID 40831018, 2025). "In addition, while PTH promotes bone formation and has therapeutic value, its bone-resorbing properties must be carefully managed to avoid exacerbating osteoporosis or other bone-related diseases." (PMID 40136530, 2025). "Excessive PTH secretion promotes osteoclastic bone resorption, leading to chronic hypercalcemia, which in turn results in osteopenia or osteoporosis, and contributes to complications, such as nephrolithiasis, neurocognitive impairment, gastrointestinal symptoms, and cardiovascular morbidities." (PMID 41227136, 2025). "They suggested that Gprc5a is a PTH (Parathyroid Hormone)-dependent gene that inhibits cell proliferation and osteoblast differentiation, and might be a suitable candidate as a drug target for osteoporosis." (PMID 40427604, 2025). "Moreover, the cyclic administration of PTH can shift the balance towards bone formation, supporting the use of PTH in conditions like osteoporosis." (PMID 40136530, 2025). "Understanding the mechanisms involved in this cascade may reveal novel targets in the treatment of osteoporosis and allow researchers a new line of approach for drug design that could overcome the “anabolic window” limiting current PTH-derived treatments." (PMID 40609791, 2025). "Chronic inflammatory conditions, where increased cytokines accelerate bone loss; prolonged corticosteroid use, which disrupts bone remodeling; and hyperparathyroidism, where excess parathyroid hormone leads to increased bone resorption, all exacerbate osteoporosis." (PMID 39070522, 2024). "An anti-sclerostin antibody is currently FDA approved as a treatment for osteoporosis and rare genetic diseases such as osteogenesis imperfecta, and the administration of PTH itself can reduce sclerostin levels." (PMID 38591777, 2024). "Similarly, PTH, the only approved anabolic drug for the treatment of osteoporosis together with the anti-sclerostin antibody Romosozumab, promotes bone formation, but also leads to increased bone resorption as a secondary effect." (PMID 38591777, 2024). "A significantly higher rate of further fractures was associated with lower BMI (body mass index) (HR 0.925, CI 0.872–0.98; p = 0.009), lower parathyroid hormone levels (HR 0.986, CI 0.973–0.998; p = 0.026) and with the diagnosis of osteoporosis (HR 2.546, CI 1.192–5.438; p = 0.016)." (PMID 39513358, 2024). "Teriparatide, a parathyroid hormone analog, is recognized for its ability to expedite recovery in older adults with osteoporosis-related fractures by improving bone mineral density (BMD) and reducing pain, which could enhance activities of daily living (ADLs)." (PMID 38614984, 2024). "In ovariectomized rats, the administration of CMD has been shown to promote osteogenesis, and the combined treatment with both CMD and parathyroid hormone (PTH) also has been demonstrated to enhance the therapeutic effect of PTH on glucocorticoid-induced osteoporosis in rats." (PMID 38628640, 2024). "Also, it has been found that one-third of the postmenopausal women with osteoporosis had increased parathyroid hormone (PTH) levels." (PMID 38299108, 2024).
osteoporosis (continued). "Typical osteoporosis treatments include bisphosphonate, estrogen agonists/antagonists, parathyroid hormone analog, calcitonin, and recently, developed drugs using the new mechanism, including monoclonal antibodies, against sclerostin and cathepsin K inhibitors." (PMID 39062525, 2024). "Low PTH remains the main driver behind low serum calcium, though the presence of pre-existing low calcium reserve, osteoporosis (especially in females), renal failure and malabsorption may play a role in low calcium levels despite a normal PTH level." (PMID 39649119, 2024). "PTH and romosozumab can be used for osteoporosis with high fracture risk but not for normal osteoporosis." (PMID 38659619, 2024). "Non-surgical treatments, including the use of medications like bisphosphonates, selective estrogen receptor modulators (SERMs), calcitonin, and parathyroid hormone analogs, are effective in delaying the onset and reducing the severity of osteoporosis manifestations." (PMID 39070522, 2024). "Next, the pathogenesis of osteoporosis is reviewed, which focuses on the regulation of parathyroid hormone and glucocorticoid, the role and regulation of Wnt/β-catenin, RANKL and other pathological signaling pathways and key regulatory factors in the development of osteoporosis." (PMID 39188952, 2024). "Additionally, they hold potential for the discovery of new PTH target genes, innovative biomarkers for the effectiveness and safety of osteoporosis-affected treatment, as well as novel therapeutic targets." (PMID 39086902, 2024). "Therefore, ACE can fight osteoporosis by increasing intestinal Ca absorption and retaining PTH to its normal level due to its high inulin content." (PMID 38247490, 2024). "Among current drug treatments for osteoporosis, a range of options such as bisphosphonates, SERMs, PTH and its analogs, RANKL inhibitors, and Sclerostin inhibitors have been confirmed to effectively increase bone density, decelerate bone loss, and lower fracture risks." (PMID 38841589, 2024). "(PTH) (teriparatide) is a potent osteoanabolic agent currently used in adult osteoporosis." (PMID 38398378, 2024). "Teriparatide is an analogue of parathyroid hormone (PTH) used for osteoporosis." (PMID 38933734, 2024). "In addition, this study did not evaluateparameters related to calcium metabolism disorders such as blood phosphorus,vitamin D, and parathyroid hormone, which are potentialmediators between osteoporosis and CVDs." (PMID 39742238, 2024). "In women, osteoporosis is attributed primarily to the loss of gonadal steroids during the menopausal transition, especially FSH, LH, and T. However, in men, low BMD was associated with high SF levels, low serum 25, OH-VD levels, and low PTH levels." (PMID 37344770, 2023). "Chronic exposure to PTH, as seen in PHPT, disrupts the equilibrium between bone formation and resorption, tilting the balance toward resorption and eventually causing bone loss and osteoporosis." (PMID 39239219, 2023). "Third, even though our control group included patients with normal calcium and PTH levels, these patients had osteoporosis which may have influenced the calcium/phosphate homeostasis." (PMID 37065752, 2023). "There were significant differences between the groups in terms of the presence of osteoporosis and PTH, bone-specific alkaline phosphatase, serum calcium, serum phosphorus, and 25-OH vitamin D levels (p = 0.001, = 0.000, = 0.000, = 0.004, = 0.000, and = 0.009, respectively)." (PMID 37113486, 2023). "T2D leads to upregulation of aldosterone and the ACE/Ang II/AT1R axis, potentially resulting in the parathyroid glands being over-stimulated and leading to increased PTH and 1,25-hydroxy vitamin D concentrations that could further lead to osteoporosis." (PMID 37569338, 2023).
osteoporosis (continued). "Of note, another study similarly showed that a 25(OH)D level less than 20 ng/mL was associated with higher PTH levels but showed no clinical difference in bone mineral density, osteoporosis, fracture, nephrolithiasis, or urinary calcium." (PMID 38115826, 2023). "Compared to untreated patients, treated patients were significantly older, had a higher proportion of men, had a lower proportion of prescriptions of other osteoporosis drugs (BPs, PTH, Menatetrenone, and SERMs) before entry, and had a higher incidence of fractures (hips and vertebrae) before entry." (PMID 37558795, 2023). "Hence, for the case of osteoporosis, optimum external PTH dose of D = 10μg daily injections, that would give a cellular responsiveness close to the healthy state." (PMID 36996072, 2023). "Calcemia and PTH increased over the years with the onset of nephrocalcinosis and the worsening of osteoporosis despite the therapy with Cinacalcet, bisphosphonates and Vitamin D. She had therefore two additional surgical procedures (parathyroid tissue without malignancy)." (PMID 36998475, 2023). "For respiratory infections, a daily supplementation of 400–1,000 IU is most effective, and osteoporosis patients are advised to take 800 IU/day, while primary hyperparathyroidism requires a higher dose of 2,800 IU/day due to the low serum calcium trait of PTH." (PMID 37426183, 2023). "This study compared the baseline characteristics of postmenopausal women in the normal and osteoporosis groups and found that the two groups had statistically significant differences in age; years since menopause; circulating IL-6, PTH, and IGFBP-3; LS BMD; and FN BMD." (PMID 37035758, 2023). "Consequently, secondary ovarian failure occurs, leading to decreased intestinal calcium absorption, increased renal calcium excretion, increased PTH secretion, increasing bone turnover, and ending in osteoporosis." (PMID 36982891, 2023). "In particular, for patients with osteoporosis who are unresponsive to or intolerant of other drugs, an anabolic agent, 1–34 PTH or teriparatide, which has been shown to increase osseointegration of implants, may be used." (PMID 37366669, 2023). "While continuous administration of PTH enhances osteoclastogenesis leading to bone resorption and calcium liberation, intermittent administration of PTH results in bone formation through enhancing osteoblast differentiation and survival, which is used as a treatment option for severe osteoporosis." (PMID 35273573, 2022). "Osteoporosis is found in 20–50% of NF1 patients, and it is associated with reduced serum 25-hydroxyvitamin D and increased serum concentrations of parathyroid hormone (PTH) and biochemical markers indicating bone turnover, such as osteocalcin or alkaline phosphatase (ALP)." (PMID 35054138, 2022). "Among antiresorptive drugs, bisphosphonates and denosumab are the most widely used in clinical practice; whereas molecules structurally related to parathormone (PTH), such as teriparatide and abaloparatide, are anabolic (i.e., bone-forming) agents frequently used to treat osteoporosis." (PMID 35629903, 2022). "Additionally, intermittent parathyroid hormone (PTH) 1-34 is another classical mediation for the treatment of osteoporosis, with the capacity of anabolic effects." (PMID 35546997, 2022). "Treatment with a cocktail of AZD4547, a pan FGFR antagonist, and teriparatide acetate, an osteoporosis drug and PTH agonist, resulted in reduced serum Ca2+, increased mineralization and increased size of certain cranial skeletal elements, including the mandible, in ta2 embryos." (PMID 35818799, 2022). "Additionally, RCS plots constructed after adjusting for PTH, history of osteoporosis, and number of days with arthritis or rheumatism as covariates also displayed U-shaped curves." (PMID 36311487, 2022).
osteoporosis (continued). "However, the intermittent administration of PTH is believed to exert a bone anabolic effect, which is why the PTH analog teriparatide is approved for the treatment of osteoporosis." (PMID 36293083, 2022). "MTIs and biological pathways associated with osteoporosis could help in further understanding the mechanism of action of PTH on bone development and osteoporosis." (PMID 36011354, 2022). "PTH treatment provides adaptations for severe osteoporosis, such as steroid-induced osteoporosis." (PMID 35675357, 2022). "PTH and OCN are also important diagnostic markers of osteoporosis." (PMID 36465653, 2022). "Target genes with the highest number of miRNAs were DGKH, TNRC6B, ZNF704, INO80D and NFAT5, but according to the literature, none of these were ever directly associated with PTH or osteoporosis." (PMID 36011354, 2022). "These miRNAs could help in further understanding the mechanism of action of PTH on bone metabolism and osteoporosis." (PMID 36011354, 2022). "PTH is an anabolic hormone used in osteoporosis treatment for a bit or a while." (PMID 36381723, 2022). "Interestingly, compared with human osteoporosis, the castrated rat model has a similar bone tissue response to estrogen, fluoride, bisphosphonate, PTH, calcitonin, and physical exercise." (PMID 35890376, 2022). "In short, the mechanism of the significant associations between GNRI and BMD and the risk of osteoporosis may be explained by an increase in IGF-I, a decrease in PTH, and resistance to muscle loss." (PMID 35656160, 2022). "Furthermore, recent studies examined zinc ́s relevance in preventing and reversing osteoporosis, acting as a local regulator of bone cells preventing PTH-induced bone resorption." (PMID 36615081, 2022). "This makes PTH-rP a more suitable candidate for osteoporosis prevention compared with PTH." (PMID 36371202, 2022). "Additionally, generalized additive models with smooth functions generated following adjustment for PTH, history of osteoporosis, and number of days with arthritis or rheumatism as covariates also showed an increase, after declining." (PMID 36311487, 2022). "PTH was the only FDA-approved anabolic treatment for osteoporosis." (PMID 36060945, 2022). "All of these miRNAs could help further explain the complex mechanism of the PTH effect on bone health and osteoporosis." (PMID 36011354, 2022). "The results showed that the baseline levels of some bone metabolism markers (PTH, Ca2+, N-MID, TPINP, and β-CTX) were positively associated with the severity of osteoporosis or fracture risk, which suggests that osteoporosis is associated with high bone turnover in our cohort." (PMID 34899374, 2021). "At present, PTH is used in osteoporosis, and its application could potentially be extended to induce vascularized bone regeneration, which in turn could be applied for optimizing implant osseointegration in aged individuals." (PMID 33925324, 2021). "Currently, osteoporosis treatment involves the use of either suppressing the osteoclast resorption (e.g., bisphosphonates, calcitonin and estrogen) or promoting new bone formation agents (e.g., parathyroid hormone, fluoride)." (PMID 34960006, 2021). "Daily subcutaneous injections of teriparatide, a recombinant form of the bioactive portion of parathyroid hormone, containing the first 34 amino acids, have been used to treat osteoporosis, prevent osteoporotic fractures and enhance fracture healing due to its net anabolic effect on bone." (PMID 34461961, 2021). "In addition, some drugs can affect serum PTH levels, for instance, the osteoporosis drugs bisphosphonate and denosumab increase the PTH level, while teriparatide decreases its level." (PMID 34899374, 2021). "A drug containing PTH is used to treat patients with another bone condition called osteoporosis, and could potentially work as a treatment for osteoarthritis pain." (PMID 33646122, 2021).
osteoporosis (continued). "Current pharmacologic drugs that are used to treat osteoporosis mainly aim to reduce excessive bone resorption (e.g. estrogen and bisphosphonates) or promote bone formation (e.g. parathyroid hormone (PTH)), and to a lesser degree a combination of both (e.g. anti-sclerostin antibody)." (PMID 34420523, 2021). "The N‐terminus of PTH has been investigated for decades for its ability to stimulate bone formation when administered intermittently (iPTH) and is used clinically as an effective anabolic agent for the treatment of osteoporosis." (PMID 34101904, 2021). "Since PTH induces osteoclasts activity, this may well represent a further mechanism contributing to osteoporosis in people with obesity." (PMID 34071985, 2021). "Moreover, teriparatide (an anabolic agent) and abaloparatide (a recombinant of PTH) can also be employed to manage osteoporosis in these patients." (PMID 34692259, 2021). "Interestingly, long-term stimulation with PTH analogue seems to increase serum Dkk-1 in women postmenopausal osteoporosis." (PMID 34093428, 2021). "It is well established that the first 34 amino acids of PTH and PTH-related peptide (PTHrP) are necessary and sufficient to fully activate the PTH/PTHrP receptor (PPR) and both PTH (teriparatide) and PTHrP (Abaloparatide) are approved anabolic agents to treat osteoporosis." (PMID 34968192, 2021). "However, with aging, along with the decreased secretion of calcitonin and estrogen, and an increase in that of parathyroid hormone, the development of osteoporosis is considered to be activated." (PMID 33728061, 2021). "Reasons for the tremendous increase may lie in the enhanced consciousness of osteoporosis assessment, bringing about the increased measurement of serum PTH and calcium and the wider application of routine biochemical screening in China at present." (PMID 33716964, 2021). "PTH can exert osteogenic effects in the human body, resulting in increased bone mass and reversing the deterioration of bone microarchitecture, which accompanies osteoporosis." (PMID 33657948, 2021). "Moreover, Cx43 seems to be essential for the anabolic proprieties of PTH when used to treat osteoporosis, as it prevents PTH-induced production of cAMP by osteoblastic cells." (PMID 34392490, 2021). "The anabolic effect of PTH on the skeleton is well-established in osteoporosis." (PMID 34760881, 2021). "PTH has also been recommended for the treatment of persistent glucocorticoid-induced osteoporosis." (PMID 33584284, 2020). "IL-17 intensified PTH-induced bone loss through the stimulation of the RANKL production in osteoblast-lineage cells, which is parallel to the roles of IL-17 in estrogen deficiency-induced osteoporosis." (PMID 32849268, 2020). "Additionally, our results demonstrated that participants with osteoporosis had higher PTH, β-CTX, P1NP, and lower 25(OH)D, consistent with previous studies." (PMID 33315972, 2020). "However, the induction of secondary hyperparathyroidism and an unambiguous role for parathyroid hormone (PTH) in the development of osteoporosis is controversial." (PMID 32582784, 2020). "Moreover, using small molecules (e.g., PTH and oxytocin) which employ endogenous stem cells for osteoporosis treatment will be intertwined in future management." (PMID 32719657, 2020). "These phenomena interfere with bisphosphonates and PTH therapeutic potentials for osteoporosis." (PMID 33584284, 2020). "Hence, on the one hand, severe vitamin D deficiency causes a mineralization problem and osteomalacia and on the other hand increased PTH content can lead to increased bone conversion, bone resorption, and osteoporosis of bone." (PMID 32103764, 2020). "So targeting the gut microbiota or T cell migration may represent novel therapeutic strategies for PTH-induced osteoporosis." (PMID 32849268, 2020). "PTH has been widely used clinically in the treatment of osteoporosis." (PMID 32075627, 2020).